IL4 (interleukin 4)
Diseases named in the same sentence as IL4 in open-access papers (continued):
Sharing a sentence is not in itself a finding about the gene and the disease.
tumor (continued). "Apoptotic cell clearance via efferocytosis polarizes tumor-associated macrophages (TAM) to adopt pro-tumor ‘M2’ wound-healing phenotypes which, by secreting cytokines such as IL-4, IL-10, IL-13 and TGF-β1, further educate Th0 or Th1 CD4 T cells towards a Th2 phenotype." (PMID 34359823, 2021). "Additionally, we confirmed that ICJ inhibited the expression of IL-4 and reversed M2 macrophage polarization in a tumor-associated condition model in vitro." (PMID 35027915, 2021). "Our hypothesis is that tumor products may act by preparing cells and making them more susceptible to IL-4." (PMID 34680504, 2021). "Human tumor associated macrophages (TAM) were treated with IL-4 and IL-13 to construct M2-TAM." (PMID 34249713, 2021). "Also, IL-4 is a potent factor that polarizes tumor-associated macrophages into type 2 cells (M2 Macrophages)." (PMID 34948183, 2021). "To determine whether transcripts of Th2/Treg-associated cytokines were detected in tumor lesions, we examined mRNA levels of Il4, Il5, and I10 in tongue tissues from 4NQO-treated mice." (PMID 33921389, 2021). "Ethanol intervention promoted the mRNA expression of epithelial-mesenchymal transition (EMT) biomarkers, such as E-cadherin, Snail, MMP-9, and also favored M2 polarization of tumor-associated macrophages by upregulating IL-4, IL-10, CD206, CXCL2, and CCL22, and downregulating IL-12 mRNA." (PMID 34771745, 2021). "Moreover, the acquisition of an M2-like phenotype is also caused by the secretion of tumor-derived cytokines such as IL4, IL10, and IL13." (PMID 33562694, 2021). "Thus, when blood monocytes attracted to the TME differentiate into tumour-associated macrophages (TAM) they can provide either anti-tumour (M1) or tumour-promoting activity (M2) as driven respectively by the local levels of IFN gamma versus IL-4/IL-13." (PMID 34202255, 2021). "Though there were no existing evidence proved that Loxl1 can direct regulate the inflammatory cytokines secretion, according to the association analysis, Loxl1 was significantly associated with intratumoral inflammation and interleukin-4 expression level in frozen tumor tissues." (PMID 34923484, 2021). "Furthermore, release of IL-4 from Th2 precipitates the activation of the alternative pathway for macrophage maturation (M2) causing further decline in the anti-tumour immune response." (PMID 32466214, 2020). "However, IL-4 and/or IL-10 alternatively activate macrophages and polarize them into tumor-associated macrophages, resulting in tumor promotion/progression." (PMID 32993179, 2020). "Like in AIT, IgG4 formed in tumor and tumor stroma is associated with chronic antigen challenge and with the Th2 cytokines IL-4 and IL-13, in combination with IL-10, released by Treg cells and M2-like macrophages in particular but also by the tumor cells themselves." (PMID 32708690, 2020). "In this model, activation of cancer cells carrying the mutated KRAS by IL-4 and IL-13, which were secreted by the Th2 cells present in the tumor microenvironment, triggered the JAK1-STAT6-MYC pathway that in turn activated glycolysis crucial for tumor progression." (PMID 33042121, 2020). "This is clinically relevant as patients with high preoperative serum interleukin-4 levels could be at high risk of postoperative tumor recurrence and, therefore, should be considered for adjuvant or neoadjuvant treatment." (PMID 33255425, 2020). "Macrophages could be developed into M2 phenotype (usually termed as tumor-associated macrophages, TAMs) induced by cytokines such as IL-4 and TGF-β." (PMID 32213179, 2020). "Accordingly, compared with WT counterparts, KO derived tumor infiltrating Treg cells upregulated the expression level of Gata3, which encodes the master transcriptional factor (TF) of Th2, as well as Th2 related cytokine IL4." (PMID 32477338, 2020).
tumor (continued). "The seeming opposing results showing enhanced cytotoxicity of IL-4/STAT6-activated as well as STAT6-deficient NK cells certainly call for a more detailed analysis of the role of STAT6 in NK cells in the context of anti-tumor and anti-viral immunity." (PMID 31781102, 2019). "IL-4 and IL-13 produced by human T helper 2 (Th2) cells, basophils, and T follicular helper cells (Tfh) induce alternative (M2) activation of macrophages and tumor-associated macrophages." (PMID 31412566, 2019). "Indeed, in a model of breast cancer, IL-4-producing Th2 cells have been shown to sustain metastasis by promoting effector functions of tumor-associated macrophages." (PMID 30909395, 2019). "In the presence of specific factors like IL-4, IL-10, and IL-13 these macrophages become polarized and differentiate into an M2-like phenotype, also called tumor-associated macrophages (TAMs) or alternatively activated macrophages (AAMs), and secrete IL-4, IL-5, and IL-6." (PMID 31323899, 2019). "We confirmed that IL-4 exerts an effect on tumor-associated macrophage polarization." (PMID 31798581, 2019). "Interestingly, Treg cell ablation resulted in increased inflammatory cytokines IL-4 and IL-5 with a concomitant reduction in classically activated tumor associated macrophages." (PMID 31555258, 2019). "Additionally, several studies have identified IL‐4 as a major regulator of the phenotypes of tumor‐associated macrophages." (PMID 29907597, 2018). "Asialyl-agalactosyl IgG, as its effect on the activation of tumor-associated macrophages, upregulated tumor-associated macrophage-related cytokines including interleukin (IL)-4, IL-10, transforming growth factor (TGF)-β1, and tumor necrosis factor (TNF)-α, in macrophagic U-937 cells." (PMID 30469416, 2018). "TAMs are typically associated with an M2-like polarization state caused by tumour-derived lactic acid or secretion of immunosuppressive cytokines such as IL-4, IL-10, and IL-13 from different cells in the tumour microenvironment or B cell-derived immunoglobulins." (PMID 28210073, 2017). "Moreover, acquisition of an M2-like phenotype is also caused by secretion of tumour-derived cytokines such as IL4, IL10, and IL13." (PMID 29065107, 2017). "As interleukins such as IL-4 and IL-10 can increase the level of M2 polarized macrophages, thus inhibiting the anti-tumor effect of non-neoplastic T-cells, Th2-associated cytokines can influence the tumor microenvironment to promote tumor progression." (PMID 29100307, 2017). "Consequently, it is only little surprising that the expression of IL-4 and IL-4Rα seems to be associated with malignant transformation in several tumor types." (PMID 28350325, 2017). "Nevertheless, IL-4Rα-knockdown also rendered the cells more susceptible to IGF-I stimulation, indicating that impaired IL-4 signaling may be compensated by other mitogens abundantly present in the microenvironment of the tumor cells in vivo." (PMID 28350325, 2017). "Both studies were able to associate larger in vivo tumor formation with functioning IL-4 signaling." (PMID 28350325, 2017). "In addition, tumor derived IL-4 can stimulate tumor-associated macrophages and promote proliferation, survival, and metastasis of tumor cells." (PMID 27895317, 2016). "Thus, our data suggests that expression of p21 is associated with the tumor growth suppressive effect of IL-4." (PMID 26993600, 2016). "Therapeutic approaches targeting Wnt5A may reduce microvascular leakage and subsequent edema formation associated with IL-4 driven pathophysiological conditions such as allergic and tumor inflammation." (PMID 27214384, 2016). "In contrast, Th2 responses, associated with cytokines IL-4, IL-5, IL-6, and IL-10, suppress Th1 activity and may anergize effector T cells to tumor antigens." (PMID 26605345, 2015). "Indeed, IL-4 and IL-13 are now considered key players in alternative macrophage generation, including tumour associated macrophages (TAMs)." (PMID 25951175, 2015).
tumor (continued). "The presence of IL13 and M-CSF in cHL cases might be responsible for the induction of MΦ-2-like CD163+ tumor-associated macrophages in cHL, whereas IL4 was detected infrequently and, if at all, seems to play a minor role." (PMID 25470820, 2014). "Taken together, potential biological links were demonstrated in our analysis; we found that IL-4 variants were present in Puerto Rican participants, and the detected variants can influence tumor infiltrating macrophage activity and their presence in and surrounding the lesions." (PMID 24278120, 2013). "Likewise, the use of a γ134.5 replication-deficient HSV-1 holding an IL-4 gene insertion, exhibited noteworthy tumor regression in intracranial models with prolonged mouse survival." (PMID 23443138, 2013). "Tumour-associated macrophages are derived from circulating monocytes and are activated macrophages of the polarised type II (type II or M2 macrophages) induced by IL-4, IL-13 (M2a) or IL-10 (M2c) and glucocorticoid hormones." (PMID 16832418, 2006). "Evidence of down-regulation of the gp200-MR6 molecule has implications for IL-4-linked toxin therapy and, as IL-4 is an inhibitor of breast epithelial growth, may represent loss of a tumour-suppression mechanism." (PMID 8932345, 1996). "IL-4, in collaboration with IL-21, is also essential for germinal center B cells maturation; we recently reported the importance of the interaction between germinal center B cells bearing Tet2 mutations and tumor cells in the pathogenesis of AITL using a murine model." (PMID 40164718, 2025). "IL-4’s role in cancer is complex; while it generally supports tumor growth, IL-4 production by cancer cells has been associated with suppressed tumor growth and loss of metastatic potential in certain models, possibly due to enhanced phagocytic behavior of tumor-associated macrophages (TAMs)." (PMID 39125732, 2024). "However, the expression levels of typical anti-inflammatory cytokines, Il4, Il10, and Il13, which are predominantly produced by tumor-associated macrophages (TAM) in the tumor microenvironment (TME), were similar between the control and creatine-supplemented groups." (PMID 37662917, 2023). "This tendency may be due to the crosstalk between myeloid-derived suppressor cells (MDSC) and tumor-associated macrophages (TAM) promoting CD4 T cell differentiation into T+H2 phenotype with IL-4 production, which in turn induces the development of M2 macrophages." (PMID 37006257, 2023). "Tumor-associated macrophages (TAMs) are recruited from circulating monocytes to tumors, where the tumor microenvironment influences them to either promote tumor resolution (M1/M(LPS)) or tumor growth, invasion, metastasis, and drug resistance (M2/M(IL-4))(recently reviewed)." (PMID 36234768, 2022). "However, IL-4 originated from tumor infiltrating lymphocytes was associated with better prognosis." (PMID 33450900, 2021). "One possible explanation is that IgG4 produced in tumor microenvironment and stroma may be associated with chronic antigen challenge associated with Th2 cytokines including IL-4, IL-10, and IL-13, which causes inappropriate host immune tolerance against malignancies and tumor progression." (PMID 33920932, 2021). "Tumor cells may secrete factors to promote Th2 and TAM2 (Tumor-Associated Macrophage) polarization, which in turn amplify this type of inflammation via IL-4, IL-5 and IL-13, suppress anti-tumor Th1 polarization and responses, and correlate with MDSC infiltrates." (PMID 33498483, 2021).
tumor (continued). "Significant decreases in the expression of cytokines are associated with tumor-associated macrophages (TAMs), including IL-4, IL-10 CCL-2, CCL-22, and CXCl-12, and suggest that the reduction in macrophages within the treated tumors could be indicative of a decrease in TAMs." (PMID 33956631, 2021). "Indeed, IL4 produced by TGF-β receptor 2 (TGFBR2)-deficient CD4+ T cells in a mouse model of breast cancer could reprogram the tumor vasculature and triggered cancer cell hypoxia and death." (PMID 34262562, 2021). "In vitro analysis of human MDMs determined that cross-linking of a surface-bound anti-tumour IgE, SF-25, induced repolarisation of subsets predominantly associated with protumour immunosuppressive and pro-repair functions, namely, M0 (unstimulated) and M2 (IL-4-stimulated) MDMs." (PMID 33081206, 2020). "Importantly, IL-4 and IL-13 are closely related to type 2 immune response-associated cytokines that induce the alternatively activated phenotype of macrophages and are known to play a prominent role in promoting tumor progression." (PMID 33352852, 2020). "To determine whether signals associated with the tumor microenvironment can alter CD11b expression and subsequently affect myeloid cell polarization, we evaluated the effect of macrophage media (mCSF-, IL-4- and IFNγ/LPS) on cell surface CD11b expression in bone marrow derived macrophages." (PMID 30568188, 2018). "Importantly, increases in TNFα, IL-12p70 and IL-2 are not merely consequent of enhanced immune cell presence, as a number of other cytokines were unaltered by ibuprofen treatment including those associated with tumor associated macrophages, monocytes and M2 polarized macrophages [IL-4, IL-6, IL-10]." (PMID 30285905, 2018). "Thus, we speculated that tumor cell-derived IL-4 would promote increased numbers of tumor-associated macrophages, and that these would be more phagocytic." (PMID 27563494, 2015). "The decreased expression of IL-4 in the tumor microenvironment of IPI-549/PD-L1 treated tumor-bearing mice further emphasizes the anti-tumor effect of combined PI3Kγ and PD-L1 inhibition." (PMID 41431358, 2026). "In preclinical models, IL-4 overexpression can rescue T cell immune functions, improving tumor control." (PMID 41596411, 2026). "Conversely, M2-TAMs are activated by T helper 2 (Th2) cytokines, such as interleukin-4 (IL-4), interleukin-10 (IL-10), macrophage colony-stimulating factor (M-CSF), or tumor cell-surface molecules 27-29." (PMID 41328341, 2026). "Flow cytometric analysis revealed a significant reduction in the number of IL-4-expressing CD8+ T-cells in tumors from dual IPI-549/PD-L1-treated tumor-bearing mice compared to IPI-549 single-agent treatment groups." (PMID 41431358, 2026). "IL-4 was shown to promote tumor cell proliferation, survival, and metastasis by enhancing anti-apoptotic signals and contributing to a pro-tumor immune microenvironment, also contributing to therapy resistance." (PMID 41596301, 2026). "RT-qPCR analysis demonstrated upregulation of anti-tumor inflammatory cytokines (IL-6, TNF-α, iNOS) and concurrent downregulation of pro-tumor factors (IL-4, IL-10), confirming successful M2 to M1 phenotype conversion with efficacy comparable to LPS treatment." (PMID 41560805, 2026). "Most notably, IL-4 induces opposite effects depending on ontogeny: promoting tumor growth, invasion, and metastasis in M-CSF-derived macrophages, while suppressing these processes in GM-CSF-derived macrophages." (PMID 41826506, 2026). "CN showed a strong efficacy in reducing IL-4 and IL-8 in both tumor cell lines, suggesting a stable action of the molecule on the pro-Th2 cytokine network." (PMID 41596301, 2026). "In our study, we decided to test IL-4 and IL-8 expressions since these two cytokines have been involved in tumor onset and progression." (PMID 41596301, 2026).
tumor (continued). "ELISA results demonstrated that circPVT1 knockdown reduced tumor cell secretion of IL4, IL10, and TGFβ, thereby promoting macrophage polarization toward the M1 phenotype." (PMID 42094010, 2026). "Macrophages induced by lipopolysaccharide (LPS) (M1/M (LPS)) promote tumor regression, while those induced by IL-4 (M2/M (IL-4)) facilitate tumorigenesis." (PMID 39781339, 2025). "By inhibiting mTOR signaling, lactate inhibits the production of interferon-γ (IFN-γ) and interleukin-4 (IL-4) by anti-tumor natural killer T (NKT) cells in the TME." (PMID 40917754, 2025). "Enrichment analysis also highlighted the involvement of interleukin -4, -13, and -17 signaling, all of which play critical roles in tumor–immune interactions." (PMID 41304910, 2025). "Studies have shown that marrow IL-4 signaling drives myeloid cell production, thereby promoting tumor progression." (PMID 40308600, 2025). "Although most cytokines changed in the tumor induced by BNT162b2 play a role in tumor-killing, there was a significant decrease in intratumoral IL-4, and significant increases in intratumoral IL-13 and peripheral IL-17A." (PMID 39743545, 2025). "IL-4-mediated macrophage programming was found to be spatially restricted, emphasizing the localized effects of cytokine gradients within the tumor." (PMID 40330466, 2025). "The other is the alternatively activated M2-like macrophage, induced by IL-13 and IL-4, which plays a role in supporting tumor growth, tissue remodeling, and promoting tumor progression." (PMID 40028336, 2025). "Higher TNF-α/IL-33 and TNF-α/IL-4 ratios in responders suggest the predominance of proinflammatory potent stimulator TNF-α of anti-tumor immune response in NET patients who responded better to therapy and diminished immunosuppressive effect of IL-33 and IL-4." (PMID 40943444, 2025). "T cell–mediated rejection of these tumors was restored by introducing interleukin-4 (IL-4) into the tumor microenvironment, either through ectopic expression or in a preclinical adoptive T cell therapy model." (PMID 40367186, 2025). "Th1 cells enhance antitumor immune responses by secreting interferon-γ (IFN-γ), while Th2 cells create an immunosuppressive TME by secreting IL-4 and IL-10, weakening cell-mediated immune responses and promoting tumor immune evasion." (PMID 40599775, 2025). "As a key regulator of the immune system, the dual role of IL-4 in the regulation of inflammation and tumor immunity provides a broad perspective for future research and treatment." (PMID 41376630, 2025). "Other types of CAR-T cells, such as 4/15NKG2D-CAR and IL-4/IL-21 ICR, also show anti-tumor activity; the former converts IL-4 inhibitory signals downstream into IL-15 activation signals, while the latter activates the STAT3 pathway." (PMID 39958351, 2025). "FOXP3 T allele deletion and HLA‐G polymorphism in the blood of patients correlate with higher STAT3 tumor expression and elevated IL‐4 and IL‐17 blood cytokines." (PMID 41263059, 2025). "Some studies have pointed out that the Th2 cells secrete IL-4 and IL-10, which promote tumor growth or metastasis by inducing immunosuppression." (PMID 39235554, 2025). "In contrast, M2 macrophages exhibit anti-inflammatory properties, promoting tumor progression, angiogenesis, and metastasis through stimulation by Th2 cytokines, including interleukin-4 (IL-4), IL-10, and TGF-β." (PMID 41502528, 2025). "Lycopene and anti‐PD‐1 treatment synergistically decrease tumor weight, tumor volume, IL‐4, IL‐10, and PD‐L1 expression." (PMID 40661795, 2025). "Research has demonstrated that Th2 cells exert pro-tumor role through the release of tumor-supporting factors IL4 and IL13." (PMID 40369667, 2025). "IL4 not only drives Th2 differentiation but also stimulates tumor cell proliferation and metastasis." (PMID 39941924, 2025).